CASP1 (caspase 1)
Diseases named in the same sentence as CASP1 in open-access papers (continued):
Sharing a sentence is not in itself a finding about the gene and the disease.
breast cancer (continued). "Therefore, we conclude caspase-1 inhibitors are promising candidates for the clinical development of anti-breast cancer drugs." (PMID 28974683, 2017). "Here, the author show that caspase-1 promotes TAMs differentiation by attenuating medium-chain acyl-CoA dehydrogenase activity and that inhibition of this axis results in suppression of tumour growth in a transgenic mouse model of breast cancer." (PMID 28974683, 2017). "Thus, it can be inferred that the activation of NLRP3 and caspase-1 in tumor parenchymal cells are mainly involved in pyroptosis and inhibit tumor growth of breast cancer, while the activation in tumor immune-stromal cells mainly contributes to inflammatory reaction and promote tumor progression." (PMID 38031068, 2023). "Moreover, caspase-1 inhibitor (YVAD) could protect breast cancer cells from DHA-induced pyroptotic cell death." (PMID 29386662, 2018). "Previous reports have shown that the activation of inflammasomes is present in the central nervous system, which support our data that caspase-1-dependent pathway is activated in the brain under certain circumstances and may regulate metastasis of breast cancer into the brain." (PMID 30042341, 2018). "Six of the genes (CASP1, CCL2, ADGRE5, IL3RA, RSPO1, and STAB1) are co‐expressed with the CH25H gene in both cancers, while two genes (ANPEP in breast cancer and CCL8 in prostate cancer) are exclusively co‐expressed with the CH25H gene in one of the tumors." (PMID 41159143, 2025). "A recent paper found that in miR-200b-transfected breast cancer cells, the levels of IL-1β, IL-18, ASC, caspase 1, and NLRP3 were firstly increased by miR-200b, then enhanced by nobiletin." (PMID 39940319, 2025). "Here the authors report that ETS1-driven caspase-1 expression is a feature of TNBC and is required for IL1β-mediated macrophage recruitment and breast cancer growth." (PMID 39353903, 2024). "Docosahexaenoic acid (DHA) inhibits breast cancer, and when it is added to the breast cancer cell line MDA-MB-231, caspase-1 and GSDMD activities are enhanced, and pyroptosis occurs, which manifests as increased IL-1β secretion and membrane perforation." (PMID 36605484, 2023). "Treatment with a caspase-1 inhibitor and NLRP3 gene silencing inhibited leptin-induced proliferation of breast cancer cells by promoting cell cycle progression and suppressing cell death." (PMID 37715239, 2023). "Quercetin, the active ingredient from the Protracted Anti-Aid Detoxification Formula, has antitumor activity in a variety of cancers and inhibits caspase-1-mediated scorching by downregulating PYD, ASC, and NLRP3 in breast cancer." (PMID 37542283, 2023). "The present study showed that expression of Casp-1, -3, -7, and -9 was increased in MCF-7 breast cancer cell lines upon treatment with the MMBL, using 100 μg/mL and 300 μg/mL, compared to non-treated MCF-7 cells." (PMID 36904007, 2023). "Without distinguishing between fibroblasts and macrophages, we found that NLRP3, caspase-1, ASC, IL-1β, and IL-18 were all elevated in the breast cancer immune-stromal cells." (PMID 38031068, 2023). "Docosahexaenoic acid triggers caspase-1 activation, GSDMD maturation, and IL-1β secretion in breast cancer cell line, MDA-MB-231, through lysosomal damage and ROS formation." (PMID 36932407, 2023). "In conclusion, our data show that small molecule inhibitors of IL1β and Caspase-1, MLX01 and VX765, are attractive therapeutic strategies for preventing breast cancer-induced bone disease." (PMID 36230739, 2022). "The expression of the IL-1-related genes, such as Il1B, CASP1 and IRAK1, have been identified to be significantly up-regulated in breast cancer compared with normal mammary tissue." (PMID 36230739, 2022). "The levels of pyroptosis signaling pathway effectors caspase-1, IL-1beta, and GSDMD involve in the invasion and metastasis of breast cancer." (PMID 34381023, 2021).
breast cancer (continued). "added DHA to breast cancer cells MDA-MB-231 and found that the activity of caspase-1 and GSDMD were enhanced, the secretion of IL-1β was increased, and showed pore-formation activity, which suggesting the occurrence of pyroptosis." (PMID 34381721, 2021). "Some authors evidenced that the retinoic acid-inducible gene (RIG-I) signaling is capable of inducing pyroptosis through of the activation of the intrinsic apoptosis pathway, of caspase-1 and of GSDMD in ER+ breast cancer cells." (PMID 33840390, 2021). "Treatment with a pharmacological inhibitor of caspase-1 and gene silencing of NLRP3 prevented leptin—induced growth of breast cancer cells via promotion of cell cycle progression and suppression of cell apoptosis." (PMID 33840390, 2021). "In particular, P2Y2R activation by ATP released from breast cancer cells induced tumor progression by regulating the inflammasome components NLRC4, ASC, and caspase-1." (PMID 32397236, 2020). "The effect of Caspase 1 inhibitor (VX765) and combination of LPS/Nigericin on NLRP3 inflammasome activity was analyzed in A549 (lung cancer), MCF-7 (breast cancer), PC3 (prostate cancer), SH-SY5Y (neuroblastoma), and U138MG (glioblastoma) cells." (PMID 33613529, 2020). "Our data suggest that adiponectin-triggered increase of CASP1 expression might be another molecular mechanism underlying the antitumoural effect of this adipocytokine, which is present in mammary epithelial cells, but has been lost in MCF-7 breast cancer cells." (PMID 18827813, 2008). "Also, numidargistat 25 is reported as a pyroptotic agent against breast cancer and various other cancers by activating GSDME, caspase-1, and caspase-3/GSDMD." (PMID 39316325, 2025). "Numerous studies have reported the capacity of anti-tumor drugs to stimulate the caspase-1-dependent cell death of tumor cells; however, the role of the NLRP3 inflammasome and pyroptosis in the breast cancer context is still ambiguous and requires in-depth molecular studies for a full understanding." (PMID 39940603, 2025). "Tetra-α-(4-carboxyphenoxy) phthalocyanine zinc (TαPcZn)-mediated PDT (TαPcZn-PDT) has shown antitumor activity in some tumor cells, but the manner in which caspase-1 is involved in the regulation of apoptosis and pyroptosis in the TαPcZn-PDT-treated breast cancer MCF-7 cells is unclear." (PMID 37630186, 2023). "In the current study, we convert to evaluate the differential expression and clinicopathological features of NLRP3 inflammasome pathway-related proteins, including NLRP3, caspase-1, ASC, IL-1β, and IL-18, in the tumor parenchymal and immune-stromal cells of breast cancer." (PMID 38031068, 2023). "For example, via caspase-1-dependent activation of proIL-1β and regulation of IL-1 secretion by GSDMD, inflammasomes support development of lung, gastric and mammary cancer, most likely through induction of inflammation and angiogenesis as well as suppression of anti-tumor immunity by IL-1β." (PMID 36581625, 2022). "This also means that proteins like caspase-1, IL-1β and GSDMD may affect the development and prognosis of breast cancer, providing new molecular targets for the clinically targeted treatment of breast cancer." (PMID 34381721, 2021). "Tumor sizes were similar between WT and Nlrp3 KO mice, indicating that NLRP3 does not support mammary tumor growth in vivo, unlike caspase-1 and ASC." (PMID 33042810, 2020). "In conclusion, in the present study, we demonstrated that P2Y2R, which is activated by ATP secreted from breast cancer cells, regulates inflammasome expression, especially the inflammasome components NLRC4, ASC, and caspase-1, ultimately resulting in increased tumor invasion and angiogenesis." (PMID 32397236, 2020). "Finally, we confirmed that P2Y2R activation by ATP mediated IL-1β and VEGF-A production and subsequent invasiveness of breast cancer cells through activation of NLRC4, ASC, and caspase-1 of inflammasome components." (PMID 32397236, 2020).
breast cancer (continued). "Since caspase-1 mediates pyroptosis cell death by triggering gasdermin D activation, we analyzed if DHA could trigger gasdermin D cleavage in breast cancer cells MDA-MB-231." (PMID 29386662, 2018). "Even though AA also induced NF-κB nuclear translocation, this fatty acid was not able to increase other pyroptosis-related parameters like active caspase-1 and secreted IL-1β, indicating that DHA-induced pyroptosis cell death triggered in breast cancer cells is a specific event." (PMID 29386662, 2018). "We did not see any correlation between BMI and CASP1 expression in HER2 or Luminal A type breast cancer." (PMID 27708283, 2016). "Although the role of caspase-1 down regulation has not been studied in breast cancer cells, it is lost in other cancer cell lines." (PMID 19422694, 2009). "They found that cisplatin could induce MDA-MB-231 cell pyroptosis via upregulating the lnc RNA MEG3 and activating the NLRP3/caspase-1/GSDMD pathway, which would accelerate the inflammatory cytokines (IL-18 or IL-1β) release and effectively treat breast cancer." (PMID 38016064, 2023). "Moreover, MEG3 was found to promote cisplatin-induced pyroptosis by promoting the NLRP3/caspase-1/GSDMD axis, implying that MEG3 may be an effective therapeutic target for enhancing breast cancer chemotherapy." (PMID 35392086, 2022). "In addition, MEG3 was found to activate cisplatin-induced cellular pyroptosis by promoting NLRP3/caspase-1/GSDMD axis, implying that MEG3 could be effective therapeutic target of breast cancer." (PMID 34488540, 2021). "Moreover, NLRC4, ASC, and caspase-1 protein levels were induced in response to TNF-α or ATP treatment in a P2Y2R-dependent manner, suggesting that the ATP released by TNF-α treatment activates P2Y2R and regulates inflammasome expression in breast cancer cells." (PMID 32397236, 2020). "Remarkably, we found that multiple genes that belong to the NLRP3 inflammasome pathway, including P2rx7, Nlrp3, Casp1, Il1a and Il1b are upregulated in CAFs isolated from mammary carcinoma, but not in normal mammary tissue, or in fibroblasts isolated from mammary hyperplasia." (PMID 31558756, 2019). "However, five genes (CDC20, MET, KIF23, ANXA1, and CASP1) that are found in the TNBC group were not highly expressed in the HR+ breast cancer subtypes but are commonly found in the ER−/PR+ and ER−/PR− groups such that they could be used as negative controls." (PMID 39000600, 2024). "While inoculation of female WT BALB/c mice with cancer cells gave rise to large tumors within 30 days, the absence of caspase-1 or ASC resulted in significantly smaller tumors, suggesting that inflammasomes likely support mammary tumor growth." (PMID 33042810, 2020). "As expected from our microarray data, adiponectin did not trigger elevated transcript levels of TR2, CASP1 and USP2 in MCF-7 breast cancer cells, but a significantly reduced USP2 expression by approximately 60%." (PMID 18827813, 2008). "Importantly, inhibiting Caspase-1 reduces bone metastasis without adversely affecting tumours outside of bone or immune cell regulation, suggesting that targeting immediately upstream of IL1β may be a good therapeutic strategy for treating patients with breast-cancer-induced bone disease." (PMID 36230739, 2022).
Stroke (56 papers, 2013 to 2025). Sudden impairment of blood flow to a part of the brain due to occlusion or rupture of an artery to the brain. "The cytosolic pattern recognition receptor NLRP3 recruits the adapter protein apoptosis-associated speck-like (ASC) pro-caspase- 1 in response to several stroke-induced stimuli." (PMID 40272769, 2025). "Inflammasome activation leads to processing of the pro-inflammatory cytokines IL-1β and IL-18 by caspase-1, and plays an important role in the inflammatory response associated with CNS injury, including stroke in rodents and humans." (PMID 39556309, 2025). "The use of both NLRP3 and Caspase-1-targeted inhibitors was effective in improving stroke symptoms, which was associated with inhibition of the pyroptosis pathway." (PMID 37165005, 2023). "Although stroke and stroke-related comorbidities can lead to enhanced caspase-1 activity, there is little clinical evidence about targeting caspase-1 in stroke or stroke-associated comorbidities nowadays." (PMID 35370546, 2022). "Caspase-1 deficiency or its inhibitors exhibit protection in experimental stroke models, as do oxygen and glucose deprivation in rat organotypic hippocampal tissue." (PMID 31555089, 2019). "The inflammatory responses to brain damage in the etiology of neurodegenerative disease and stroke have been implicated to be mediated by the NLRP3 inflammasome and its activation/related products, TXNIP, ASC specks, caspase- 1, and IL- 1β." (PMID 40272769, 2025). "For time-to-event analysis, MPO-DNA, Caspase-1 and IL-1β at baseline were predictors of MVEs after stroke (HR:4.04 (95%CI 1.28-12.70), 2.33 (95%CI 1.06-5.12) and 4.09 (95%CI 1.39-11.99), respectively)." (PMID 39737165, 2024). "Both depletion of the neutrophil population and inhibition of PAD4 efficiently prevented the post-stroke increase in blood cfDNA levels and reduced caspase-1 activation to levels in Sham-operated control mice." (PMID 39112714, 2024). "Caspase-11 is one of several upstream caspases in the cascade that mediates the activation of both caspase-1 and caspase-3, which can result in cytokine release and/or apoptosis, respectively, leading also to stroke induction." (PMID 39625520, 2024). "Exercise preconditioning inhibited the protein expression of NLRP3, Caspase-1, IL-18, and IL-1β to improve cognitive dysfunction in stroke mice." (PMID 38317957, 2024). "Eukaryotic cells can initiate several self-destruction programs, with caspase-1-dependent cell death (known as pyroptosis) representing an intrinsic inflammatory response triggered by various pathological stimuli, such as stroke, heart disease, or cancer." (PMID 39011036, 2024). "Male MMP-3 KO stroke brains also exhibited downregulation of apoptosis-related genes such as Casp9, Casp7, Bmf, Casp1, Bid, Casp6, Casp3, Casp2, Fas, Casp4, and Casp8." (PMID 39000490, 2024). "Inhibit the activation of NLRP3 inflammasome and Caspase-1, and to regulate their upstream related signaling pathways, reduce post-stroke pyroptosis and the related inflammation." (PMID 39312329, 2024). "By contrast, neutralization of cfDNA after stroke by therapeutic administration of recombinant DNase following stroke induction again significantly reduced the plaque inflammasome activation, as measured by caspase-1 cleavage and IL-1β secretion." (PMID 39112714, 2024). "Pyroptosis, a form of caspase-1-dependent cell death, also known as inflammation-dependent death, plays a crucial role in diseases such as stroke, heart disease, or tumors." (PMID 39011036, 2024). "Blocking inflammasome activity by a caspase-1 inhibitor (VX765) prevented the proliferation of immune cells within CCA plaques after stroke and attenuated the invasion of pro-inflammatory circulating monocytes." (PMID 39112714, 2024).
Stroke (continued). "NLRP1 is predominantly expressed in neuronal cells after stroke and, owing to its unique pyrin structural domain, can bind directly to procaspase-1, thereby facilitating Caspase-1 cleavage of GSDMD with the pro-inflammatory factor IL-1." (PMID 37165005, 2023). "It is well known that pyroptosis is highly dependent on Caspase-1; thus, Caspase-1 inhibitors also have great potential as drugs for stroke treatment." (PMID 37165005, 2023). "The disruption of astrocytes together with aquaporin 4 unpolarization occurs in stroke subsequently, which can be reversed via targeting caspase-1, especially among the diabetics." (PMID 35370546, 2022). "Meanwhile, despite the direct activation of caspase-1, several comorbidities along with stroke can exacerbate caspase-1 activation toward unfavorable outcomes." (PMID 35370546, 2022). "Ritonavir, once a protease inhibitor used to treat HIV, was later found to effectively reduce the level of IL-18 in mouse pancreatic cancer by suppressing caspase-1 activation with the potential application in stroke." (PMID 35370546, 2022). "We detected the expression of three inflammasomes, AIM2, NLRC4, and Caspase-1 using immunofluorescence and found that the expression of the three inflammasomes was significantly decreased in stroke rats after THSWD administration." (PMID 36034843, 2022). "NLRP3 inflammasome and pro-inflammatory cytokines such as IL-1 β and caspase-1 were highly expressed in cellular and animal models of stroke, as well as in stroke patients." (PMID 36160384, 2022). "Although IL-18 was shown to mediate inflammatory response resulting in loss of appetite, sleep dysregulation, and several neurodegenerative diseases, caspase-1 mediated IL-18 on BBB in stroke deserves further exploration." (PMID 35370546, 2022). "It is found that the classical caspase-1 signaling pathway mediating pyroptosis is activated in stroke and aggravates brain injury, while inhibiting caspase-1 activation can reduce stroke injury and play a protective role." (PMID 35600074, 2022). "The encapsulation rate of pericytes, which is crucial for the maintenance of microvasculature and is usually decreased during a stroke, can be elevated via caspase-1 inhibition." (PMID 35370546, 2022). "By comparison, it was found that the expression levels of AIM2, NLRC4, and Caspase-1 were significantly inhibited in the I/R + THSWD group after the gavage of THSWD to stroke rats." (PMID 36034843, 2022). "A process that drives neuroinflammation in stroke, for example, a rise in caspase-1 cleavage and release of IL-1β, results from the activation of the NLRP3." (PMID 36138981, 2022). "Considering that caspase-1 can be expressed on BBB, in this part, we will focus on caspase-1-dependent effects on BBB structures during a stroke." (PMID 35370546, 2022). "Meanwhile, since the effects share resembling characteristics in various patterns of ischemic and hemorrhagic stroke, caspase-1-dependent effects on BBB will be concerned with stroke events as a whole." (PMID 35370546, 2022). "Our review sheds light on caspase-1 as a promising and crucial target throughout stroke intervention in the coming future." (PMID 35370546, 2022). "We found that NBP significantly reduces neuron and CASP1+ neuronal death on 3 days after stroke, suggesting that NBP treatment partially reduces neuronal death caused by pyroptosis." (PMID 36013423, 2022). "It has been reported that it was Caspase-8 that played a decisive role in multiple sclerosis, whereas our data suggested that it was Caspase-1/-11 that represented the primary executors in post-stroke inflammasome activation." (PMID 33967935, 2021). "Caspase-1 activity, IL-1β, TNF-α, and NLRP3 have been demonstrated to be associated with modulation of apoptosis after stroke, causing activation of caspase-dependent pathways of cell death." (PMID 34257822, 2021).